LEMD1 (LEM domain containing 1)
Diseases named in the same sentence as LEMD1 in open-access papers (continued):
Sharing a sentence is not in itself a finding about the gene and the disease.
cancer (10 papers, 2020 to 2023). A tumor composed of atypical neoplastic, often pleomorphic cells that invade other tissues. "Our pan-cancer analysis consistently showed that LEMD1 is overexpressed in various cancers and is associated with shorter survival of tumor patients." (PMID 37296887, 2023). "In summary, our findings not only provided insight into understanding the mechanism underlying the regulation of cancer cell proliferation and migration by LEMD1, but also laid a solid foundation for the development of a novel oncogene and therapeutic target for TNBC treatment." (PMID 37296887, 2023). "Although we found that LEMD1 could promote cancer cell proliferation, the underlying mechanisms remained still unknown." (PMID 35286235, 2022). "Next, we analyzed the prognostic value of LEMD1 in pan-cancer and found that high expression of LEMD1 was significantly associated with worse OS rate in COAD (p = 0.047), KIRC (p = 0.0065), KIRP (p = 0.023) and PAAD (p = 0.0027)." (PMID 37296887, 2023). "It has been reported that LEMD1 is upregulated in various kinds of malignancies and facilitates cancer progression." (PMID 37296887, 2023). "Firstly, we analyzed LEMD1 expression in various cancers by comparing the transcriptome data between tumor tissues and corresponding adjacent normal tissues." (PMID 37296887, 2023). "It has been reported that LEMD1 ABRACL is a regulator of the actin cytoskeleton and cell motility and is closely associated with invasion and metastasis of human cancers." (PMID 35341461, 2022). "As reported in recent decades, LEMD1 was upregulated in several cancers and played key roles in cancer progression." (PMID 35286235, 2022). "All the results in this aspect suggested that LEMD1 facilitated cancer cell aggressiveness via mTORC1 signaling in PC." (PMID 35286235, 2022). "Of the function, LEMD1 knockdown inhibited cancer cell growth, migration and invasion, while LEMD1 overexpression promoted tumor aggressiveness." (PMID 35286235, 2022). "As presented, ectopic LEMD1 increased the proliferative rate of cancer cells, which was alleviated by rapamycin." (PMID 35286235, 2022). "Of importance, multiple tumor aggressiveness has been attributed to the dysregulation of LEMD1 in certain cancer, for instance, including cancer cell proliferation, cell cycle, cell apoptosis, metastasis and endothelial transmigration." (PMID 35286235, 2022). "The expression of LEMD1 in cancer tissues was almost fourfold higher than that in the adjacent healthy tissues." (PMID 34672237, 2021). "Depletion of LEMD1 in various cancer cell types decreased cell growth, invasiveness, and epithelial–mesenchymal transition; however, a specific cellular function for LEMD1 has yet to be determined." (PMID 34685604, 2021). "We found that high expression of LEMD1 was markedly associated with higher histology grade of TNBC patients, suggesting that LEMD1 may act as a cancer-promoting factor in TNBC." (PMID 37296887, 2023). "LEMD1 exerts oncogenic effects during tumorigenesis of various cancers." (PMID 37296887, 2023). "The other family members, LAP2 and LEMD1, were reported to be upregulated in various cancers." (PMID 35650630, 2022). "As depicted, the productions of CDK2 and SKP2 were positively regulated by LEMD1 in cancer cells." (PMID 35286235, 2022). "In recent decades, LEMD1 has been reported to facilitate cancer aggressiveness known as follows." (PMID 35286235, 2022). "As depicted, LEMD1 knockdown significantly increased the percentage of apoptotic cancer cells." (PMID 35286235, 2022). "Previous studies have identified LEMD1 as an oncogene in various cancers." (PMID 34672237, 2021).
cancer (continued). "Because CT antigens are useful targets for cancer vaccination and immunotherapy through the activation of cytotoxic T lymphocytes, LEMD1 may be a useful candidate for molecular targeted therapy for OSCC." (PMID 32455867, 2020). "Although LEMD is a cancer-testis antigen, the cancer-related signals related to LEMD1 remain unknown." (PMID 32455867, 2020). "Moreover, LEMD1 facilitates cancer cell invasion and promotes the adhesion and transmigration of OSCC cells to vascular and lymphatic endothelial cells." (PMID 32455867, 2020). "LEMD1 also plays a pivotal role in the maintenance of cancer stem cells in colon cancer." (PMID 32455867, 2020). "LAP2, emerin, MAN1 (LEM) domain containing 1 (LEMD1) is a novel cancer-testis (CT) antigen." (PMID 32455867, 2020). "LEMD1 could function to be a meaningful marker for the prognosis and progression of such cancers." (PMID 35286235, 2022). "However, little is known about LEMD1 downstream signaling in cancer." (PMID 32455867, 2020). "In view of the critical role of LEMD1 in TNBC, we performed pan-cancer analysis to gain a more comprehensive understanding of LEMD1 in various cancers." (PMID 37296887, 2023). "LEM domain containing 1 (LEMD1) is overexpressed in multiple tumor tissues and plays a key role in cancer carcinogenesis and progression." (PMID 35286235, 2022). "LEMD1 (LEM domain containing 1) belongs to cancer testicular antigen (CTA), which is only expressed in normal testes, and oncogenic CTA is the target of cancer immunotherapy." (PMID 35619906, 2022). "The core CT genes include CMTM1, CT83 (CXorf61), EZHIP (CXorf67), DCAF4L2, KHDRBS3, LEMD1, PIWIL1, and SPATA6, which contribute to cancer progression and metastasis." (PMID 33426787, 2021).
tumor (8 papers, 2014 to 2023). "Additionally, they found that the sushi repeat-containing protein X-linked 2 (SRPX2) is a downstream signal of LEMD1, which acts as a tumor genesis gene in OSCC." (PMID 34672237, 2021). "To extend the in vitro observations, we constructed a subcutaneous xenograft model in female nude mice to investigate the influence of LEMD1 silencing on tumor growth in vivo." (PMID 37296887, 2023). "LEMD1 knockdown combined with paclitaxel exhibited a stronger inhibitory effect on tumor cell proliferation compared to treatment with paclitaxel alone." (PMID 37296887, 2023). "Taken together, these studies demonstrate that LEMD1 plays a pivotal role in promoting tumor progression, suggesting its clinical value as a potential prognostic biomarker and therapeutic target in diverse tumors." (PMID 37296887, 2023). "No tumor formation was observed in MDA-MB-231 cells with knockdown of LEMD1 expression, indicating that LEMD1 silencing totally abolished tumor formation in vivo." (PMID 37296887, 2023). "LEMD1 was highly expressed in CRC cells among 22 common tumor cells (1060 strains), and the highest expression was found in SW480." (PMID 35619906, 2022). "We previously reported that LEMD1 is closely involved in tumor progression, nodal metastasis, and worse OSCC outcomes by acquiring invasiveness and angiogenic and lymphangiogenic potential." (PMID 32455867, 2020). "The model constructed by LEMD1, SERPINE1, and SIAE could easily predict the risk of postoperative recurrence, implying that these hub genes may play a key role in tumor occurrence and development." (PMID 35619906, 2022). "The tumor-promoting influences of LEMD1 in PC were also proved by in vivo assays." (PMID 35286235, 2022). "LEMD1 expression in tumor cells was tested by RT-qPCR and western blotting." (PMID 35294319, 2022). "Therefore, we believe that RhoA is a downstream regulator of LEMD1, and LEMD1 could affect cytoskeleton changes and tumor cell migration in part through the RhoA/ROCK1 signaling pathway." (PMID 35619906, 2022). "Silencing of LEMD1 not only inhibits the proliferation, migration and invasion abilities of TNBC cells in vitro, but also abolishes tumor formation of TNBC cells in vivo." (PMID 37296887, 2023). "LEMD1 silencing not only inhibited the proliferation and migration of TNBC cells in vitro, but also abolished tumor formation of TNBC cells in vivo." (PMID 37296887, 2023). "CT46 expression was found in 7/23 (30.4%) and LEMD1 in 8/23 (34.8%) DCIS samples and in 1/12 (8.3%) and 3/12 (25%) benign lesions, respectively." (PMID 25593980, 2014). "Furthermore, LEMD1 silencing not only inhibited the proliferation and migration of TNBC cells in vitro, but also abolished tumor formation of TNBC cells in vivo." (PMID 37296887, 2023). "Therefore, we concluded that LEMD1 affected cytoskeletal changes by activating the RhoA/ROCK signaling pathway, thus promoting EMT and tumor metastasis." (PMID 35619906, 2022).
LEMD1 also shares sentences with these, for which no sentence is quoted: Alzheimer disease (1 paper); basal cell carcinoma (1); cervical squamous cell carcinoma (1); melanoma (1); ovarian carcinoma (1); ovarian serous cystadenocarcinoma (1); triple-negative breast carcinoma (1).